MYD88 (MYD88 innate immune signal transduction adaptor)
Diseases named in the same sentence as MYD88 in open-access papers (continued):
Sharing a sentence is not in itself a finding about the gene and the disease.
pulmonary fibrosis (28 papers, 2012 to 2026). Chronic progressive interstitial lung disorder characterized by the replacement of the lung tissue by connective tissue, leading to progressive dyspnea, respiratory failure, or right heart failure. "Research has shown that autophagy participates in the progression of pulmonary fibrosis, and MyD88 is closely associated with autophagy." (PMID 41007776, 2025). "The proinflammatory role of TLR4-MD2 complex and Myd88 signaling pathway in the lungs has also been evaluated and associated with the fibrotic process leading to pulmonary fibrosis." (PMID 34367191, 2021). "Loss of MyD88 reduced the influx of immune cells as well as lung inflammation and the development of pulmonary fibrosis." (PMID 28836991, 2017). "We additionally show that pulmonary fibrosis in MyD88-KO mice was associated with the accumulation of pro-fibrotic regulatory T lymphocytes (T regs) and pro-fibrotic cytokine expression (TGF-β, IL-10 and PDGF-B), not with T helper (Th) 17 cell influx." (PMID 25050810, 2014). "Altogether, these results indicated that the development of lung fibrosis in MyD88-KO mice is rather associated with the presence of immunosuppressive T regs than with inflammatory Th17 lymphocytes." (PMID 25050810, 2014). "Silica-induced pulmonary inflammatory and granulomatous responses are related to MyD88-dependent innate immunity while lung fibrosis is uncoupled from this pathway and linked to T reg-related immunosuppression." (PMID 25050810, 2014). "MyD88 is a key adaptor protein involved in innate immune signaling, particularly in the pathogenesis of lung injury and pulmonary fibrosis." (PMID 41596433, 2026). "Our results showed that MyD88 expression was positively correlated with pulmonary fibrosis and lung fibroblast activation." (PMID 41007776, 2025). "In this study, we used TJ-5 as an effective MyD88 inhibitor; therefore, we investigated the therapeutic effects of TJ-5 on pulmonary fibrosis in mice and elucidated the impacts on autophagy." (PMID 41007776, 2025). "Studies have demonstrated that the activated NLRP3 inflammasome can promote pulmonary EMT via the IL-1β/IL-1Rs/MyD88/NF-κB signaling pathway, leading to pulmonary fibrosis." (PMID 40391214, 2025). "It is worth mentioning that this is the first time that MyD88 has been shown to regulate autophagy in lung fibrosis." (PMID 41007776, 2025). "Mechanistically, diazepam can upregulate the expression of let-7a-5p, inhibit the expression of MYD88, and reduce inflammation and inhibit pulmonary fibrosis by regulating the let-7a-5p/MYD88 axis." (PMID 38875245, 2024). "In conclusion, we demonstrated that diazepam inhibits LPS-induced pyroptosis and inflammation and reduces the incidence of pulmonary fibrosis in mice by regulating the let-7a-5p/MYD88 axis." (PMID 38875245, 2024). "This study can increase the selection of diazepam for drug screening in the treatment of pulmonary fibrosis and provide new potential therapeutic targets for let-7a-5p and MYD88 for molecular target treatment of pulmonary fibrosis." (PMID 38875245, 2024). "This study also showed that the expression of MYD88 and IL-1β significantly increased in LPS-induced pulmonary fibrosis, whereas the overexpression of let-7a-5p significantly downregulated the expression of MYD88." (PMID 38875245, 2024). "Our findings indicated that diazepam can inhibit LPS-induced pyroptosis and inflammatory responses and alleviate pulmonary fibrosis in mice by regulating the let-7a-5p/MYD88 axis." (PMID 38875245, 2024). "It has been reported that the expression of MYD88 and IL-1β is increased in bleomycin-induced pulmonary fibrosis in mice." (PMID 38875245, 2024). "The hESC-MSC-IMRC-CM can significantly inhibit BLM-induced pulmonary fibrosis in mice by inhibiting the production of ROS and proinflammatory cytokines by regulating Nox4/Nrf2 and Tlr4/MyD88 signaling pathway, respectively." (PMID 36830999, 2023).
pulmonary fibrosis (continued). "Inflammation is an initial driver of PF, and toll-like receptor 4 (TLR4)/MyD88-mediated inflammation and inflammatory cytokines have shown a profibrotic effect in the development of pulmonary fibrosis." (PMID 36830999, 2023). "A functional study has suggested that miR-489 is negatively mediated by lncRNA CHRF and can target Myd88, which engages in silica-induced pulmonary fibrosis." (PMID 35711847, 2022). "We showed that TLR4, MD2, Myd88, and related pathways are significantly induced in lungs collected on day 14 of bleomycin-induced pulmonary fibrosis." (PMID 34367191, 2021). "Pulmonary fibrosis was also exacerbated in MyD88−/− mice in response to intratracheal BLM administration." (PMID 28836991, 2017). "Consistently with this finding, our studies showed that MyD88 and IL-1β were increased in pulmonary fibrosis and that inverse levels of MyD88 and IL-1β were observed after the overexpression of miR-489." (PMID 27506999, 2016). "Our molecular study further demonstrated that miR-489 inhibited silica-induced pulmonary fibrosis primarily by repressing its target genes MyD88 and Smad3." (PMID 27506999, 2016). "Most notably, these results strongly suggest that lncRNA CHRF, by targeting miR-489, regulates its targets MyD88 and Smad3 and participates in activating inflammation and pulmonary fibrosis." (PMID 27506999, 2016). "This study is the first to report that miR-489 attenuates silica-induced pulmonary fibrosis by directly repressing MyD88 and Smad3, and that it is regulated by CHRF." (PMID 27506999, 2016). "The overexpression of miR-489 blocked pulmonary fibrosis both in vivo and in vitro by regulating its target genes MyD88 and Smad3, which are critical mediators in the inflammation and fibrotic signaling pathways, respectively." (PMID 27506999, 2016). "In conclusions, less organized lung fibrosis was observed in these MyD88/IL-1 family-related models." (PMID 25050810, 2014). "Histological analyses revealed that while pulmonary fibrosis was localized in granulomas in WT animals, it was diffusely distributed throughout the parenchyma in MyD88-KO mice." (PMID 25050810, 2014). "Based on these findings, we aimed to determine whether MyD88 inhibition-induced autophagy in pulmonary fibrosis is related to mTOR, PI3K/AKT, and MAPK." (PMID 41007776, 2025). "Overall, autophagy may be a critical target for TJ-5-mediated MyD88 inhibition, interfering with pulmonary fibrosis." (PMID 41007776, 2025). "Additionally, preclinical models of pulmonary fibrosis show that the expression levels of MyD88 in lung tissue increase after exposure to various profibrotic stimuli." (PMID 40391214, 2025). "Therefore, this study demonstrated that diazepam can upregulate the expression of let-7a-5p and inhibit the expression of MYD88 to reduce pyroptosis and inflammation, thus ultimately alleviating the progression of pulmonary fibrosis." (PMID 38875245, 2024). "We further confirmed whether diazepam can alleviate the progression of pulmonary fibrosis by regulating the let-7a-5p/MYD88 axis through cell pyroptosis and the inflammatory response." (PMID 38875245, 2024). "Therefore, the suppression of inflammation through the TLR4/MyD88/NF-κB pathway in an early stage of the fibrosis process can effectively improve lung fibrosis." (PMID 35178456, 2022). "Interestingly, a prior report demonstrated increased lung fibrosis following C. pneumoniae infection in IL-1RI KO mice, which also utilizes MyD88 for signaling, although the frequency of M2 macrophages was not examined." (PMID 22879997, 2012). "However, whether inhibition of MyD88 affects autophagy activity during pulmonary fibrosis remains unclear." (PMID 41007776, 2025). "However, whether targeting MyD88 can affect fibrosis progression by regulating autophagy during lung fibrosis remains unclear." (PMID 41007776, 2025).
pulmonary fibrosis (continued). "Therefore, the purpose of this study was to determine whether diazepam can inhibit inflammation and ameliorate pulmonary fibrosis by regulating the let-7a-5p/myeloid differentiation factor 88 (MYD88) axis." (PMID 38875245, 2024). "The hESC-MSC-IMRC-CM-mediated amelioration of pulmonary fibrosis was through a mechanism by suppressing the BLM-induced oxidative stress and inflammation via respective Nox4/Nrf2 and Toll/MyD88 signaling pathways." (PMID 36830999, 2023). "The levels of ST2, MyD88, and TRAF6 proteins in bleomycin-induced pulmonary fibrosis tissues were elevated." (PMID 35046838, 2021). "Our previous study also demonstrated that the injection of human placental MSCs of fetal origins (hfPMSCs) could significantly alleviate BLM-induced pulmonary fibrosis with the decrease in Hyp and pro-fibrotic cytokines in mice by inhibiting the TLR/MyD88 signaling pathway." (PMID 36830999, 2023). "However, MyD88-KO mice developed pronounced lung fibrosis even in the absence of progressive inflammation indicating that fibrogenesis is a pathological process, which can also occur independently of inflammatory and innate immune responses." (PMID 25050810, 2014).
pancreatic cancer (27 papers, 2017 to 2025). "Together, these data indicate that loss of MyD88 in the myeloid compartment improves pancreatic cancer response to RT, which cannot be observed with total MyD88 loss." (PMID 37244938, 2023). "F. nucleatum can also cause the immunosuppression of the pancreatic cancer microenvironment through the same MyD88 pathway." (PMID 34326701, 2021). "MYD88 is a significant target for innovative therapies in pancreatic cancer due to its crucial molecular role in linking various upstream ligand–receptor complexes." (PMID 39065761, 2024). "We generated Myd88 conditional knockout mice to interrogate its contribution to the immune response to radiation therapy in distinct immune populations in pancreatic cancer." (PMID 37244938, 2023). "Tumour-promoting protein PAUF secreted by cancer cells promotes the migration of human pancreatic cancer cells through TLR4/MyD88 signal." (PMID 38052785, 2023). "These are consistent with several studies which have shown that overexpression of DMKN enhances the proliferation and epithelial–mesenchymal transition of pancreatic tumor cells; MyD88 in myofibroblasts can promote macrophage M2 polarization." (PMID 36944954, 2023). "Together, these data indicate that MYD88 and TLRs are heterogeneously expressed in pancreatic cancer, with granulocytes, B cells, and cells of the macrophage/monocyte lineage expressing high levels of TLRs that signal through MyD88." (PMID 37244938, 2023). "Surprisingly, Myd88 deletion in Itgax (CD11c)-expressing dendritic cells had little discernable effects on response to RT in pancreatic cancer and elicited normal T cell responses using a prime/boost vaccination strategy." (PMID 37244938, 2023). "The current study not only shows that PAUF can bind directly to TLR4 on pancreatic cancer (PC) cell surfaces and promote cell migration exclusively through the MyD88-dependent pathway." (PMID 36232715, 2022). "In the murine models, the TLR4/MyD88 pathway can trigger protection from pancreatic cancer development or acting to promote inflammation and pancreatic cancer development." (PMID 33193429, 2020). "We next determined which cell types express Myd88 and TLRs in murine pancreatic tumors." (PMID 37244938, 2023). "Whether through these or additional mechanisms, it remains evident from our experiments that myeloid MyD88 signaling restricts production of type I interferon in response to RT, thereby limiting adaptive immune control of tumors in pancreatic cancer." (PMID 37244938, 2023). "Our results indicate that the MyD88 pathway in myeloid cells may limit RT-mediated immune control of pancreatic cancer and agonists avoiding inflammatory MyD88 signaling or myeloid-specific MyD88 inhibition may be alternative strategies to improve outcomes." (PMID 37244938, 2023). "In addition, blockade of the MyD88-independent TRIF pathway is protective against pancreatic cancer, whereas blockade of the MyD88-dependent pathway surprisingly exacerbates pancreatic inflammation and malignant progression." (PMID 33520714, 2020). "Whereas TLR4−/− mice showed decreased tumour growth in a murine model of pancreatic cancer, inhibition of MyD88 accelerated tumour development as well as an increased TLR4 expression correlated with tumour size, lymph node involvement, venous invasion and pathological stage." (PMID 28572836, 2017). "Mechanistically, circCUL2 functioned as a ceRNA and modulated the miR-203a-3p/MyD88/NF-κB/IL6 axis, thereby further activating the STAT3 signaling pathway in pancreatic cancer cells to induce PDAC progression." (PMID 35189958, 2022). "Mechanistically, circCUL2 functioned as a ceRNA and modulated the miR-203a-3p/MyD88/NF-κB/IL6 axis, thereby further activating the STAT3 signaling pathway in pancreatic cancer cells to induce the progression of PDAC." (PMID 35189958, 2022).
pancreatic cancer (continued). "LPS has been shown to promote the development of pancreatic cancer by blocking the MyD88-dependent pathway while blocking TLR4 and MyD88-independent pathway has a protective effect on pancreatic cancer." (PMID 36003766, 2022). "circCUL2 functioned as a ceRNA and modulated the miR-203a-3p/MyD88/NF-κb/IL6 axis, inducing the conversion of NFs into iCAFs, thereby further activating the STAT3 signaling pathway in pancreatic cancer cells to induce the progression of PDAC." (PMID 35189958, 2022). "Our data suggests that while both BCR and MyD88 signaling in B cells promote IL-35 expression in vitro, BCR signaling plays a dominant role in IL-35 expression in vivo in response to pancreatic cancer." (PMID 35046933, 2021). "However, our scRNASeq analysis of TLR and MyD88 expression in the PK5L1940 tumors derived from KPC-LSIY mice and patient pancreatic tumors suggest similar cells and pathways are involved in both settings." (PMID 37244938, 2023). "TLR4 and MyD88 were found to be significantly increased in a concentration-dependent manner in PANC-1 and BxPC-3, which hinted that stimulating TLR4 led to positive feedback in pancreatic cancer cells." (PMID 34718325, 2021). "However, in vivo, B cell receptor activation, as opposed to MyD88 signaling in B cells, is central to B cell-mediated suppression and promotion of pancreatic cancer growth." (PMID 35046933, 2021).
Cerebral ischemia (26 papers, 2012 to 2026). Restriction of arterial blood supply to the brain associated with insufficient oxygenation to support the metabolic requirements of the tissue. "Overall, it is noteworthy that the cytokine profile obtained from our MyD88−/− mice following cerebral ischemia was similar to the cytokine profile obtained when whole-blood cells from patients with deficiencies of MyD88 were stimulated with specific TLR agonists." (PMID 22799573, 2012). "In conclusion, XMZS exerts neuroprotective effects against cerebral ischemia-reperfusion injury by modulating the TLR4/MYD88/NF-κB pathway, thereby attenuating microglia-mediated neuroinflammation." (PMID 42005317, 2026). "Numerous evidence has revealed that the TLR4 and TLR4-mediated MyD88-NF-κB signaling pathway play an important role in the regulation of the inflammatory reaction in a cerebral ischemia injury." (PMID 34712659, 2021). "MyD88-dependent signaling contributes to the inflammatory responses induced by cerebral ischemia/reperfusion." (PMID 32746852, 2020). "Cerebral ischemia/reperfusion activates the TLR4-mediated MyD88-dependent pathway and upregulates NF-κB." (PMID 32479555, 2020). "Toll-like receptors have a number of downstream effects following cerebral ischemia, including MyD88-directed activation of neutrophil chemoattractants, and this process was predicted to be increased in females in this study." (PMID 25036109, 2014). "Neither is there an apparent neuroprotective effect by disruption of the TLR downstream adaptor proteins MyD88 or TRIF against cerebral ischemia." (PMID 23097717, 2012). "G-CSF, another neutrophil chemoattractant, which was produced in a MyD88-dependent manner in our study, has been shown to increase in the brain following cerebral ischemia in humans." (PMID 22799573, 2012). "The production of G-CSF in a MyD88-dependent manner following cerebral ischemia in our current study is supported by findings of significantly reduced G-CSF levels in MyD88−/− mice in models of infection." (PMID 22799573, 2012). "These combined results strengthen our conclusion that the MyD88 pathway is involved in neutrophil migration to the site of cerebral ischemia." (PMID 22799573, 2012). "Analgecine (AGC), an analgesic for lumbar pain in patients with spinal degenerative diseases, has been shown to inhibit M1-type polarization and promote M2-type polarization by inhibiting TLR4/MyD88/NF-κB signaling pathway, which reduced neuroinflammation during cerebral ischemia." (PMID 37361996, 2023). "Therefore, it is difficult to precisely modulate the expression of Myd88 in brain ischemia in order to balance its pro-inflammatory and anti-infection properties." (PMID 37234258, 2023). "Thus, our studies are the first to show that vinpocetine also exerts an anti-inflammatory effect by inhibiting the TLR4/MyD88/NF-κB signaling pathway in a cerebral ischemia and reperfusion model." (PMID 29113305, 2017). "A recent study showed that a compensatory Th2-type skew at baseline in MyD88−/− mice and a paradoxical switch to a Th1 phenotype following focal cerebral ischemia; additionally, the MyD88 pathway directs the expression of neutrophil chemoattractants following cerebral ischemia." (PMID 25928750, 2015). "It is intriguing that despite that there are several studies demonstrating neuroprotection in TLR2 and TLR4-deficient animals following cerebral ischemia, KO of the gene for the downstream adaptor molecule, MyD88, does not provide protection." (PMID 23097717, 2012). "Finally, the MyD88 pathway directs the expression of neutrophil chemoattractants following cerebral ischemia." (PMID 22799573, 2012). "Pellino1 positively regulates the production of inflammatory factors in MyD88-dependent TLR signaling as MyD88 deficiency hindered the expression of Pellino1, NF-κB, IL-1β, IL-6, Beclin-1, and cyclooxygenase-2 (COX-2) in a cerebral ischemia/reperfusion (I/R) mouse model." (PMID 35197966, 2022).